SCN1A (sodium voltage-gated channel alpha subunit 1)
Diseases named in the same sentence as SCN1A in open-access papers (continued):
Sharing a sentence is not in itself a finding about the gene and the disease.
Dravet syndrome (continued). "Proband 8 has a variant in SCN1A, p.R187Q; however, this variant was inherited from an unaffected father, is present in gnomAD in one heterozygote, and, according to the referring clinician, the phenotype observed in the proband is not consistent with Dravet syndrome." (PMID 30500825, 2018). "However, this analysis may have been confounded by many factors: effects may be brain-region or cell-population specific, as in SCN1A-related Dravet syndrome, where consequences are only found in interneurons; our whole-tissue expression analysis would not detect such subtle signals." (PMID 24014518, 2013). "For example, Scn1a+/− mice with decreased Cacna1g (Cav3.1) expression showed improved survival and reduced spontaneous seizure frequency, suggesting CACNA1G as a possible genetic modifier and a potential drug target for Dravet syndrome patients." (PMID 39513870, 2024). "In conclusion, the MEPIRAPIM analogue SB2193 has acute anticonvulsant effects in the 6 Hz mouse model of psychomotor seizures but not the Scn1a+/− mouse model of Dravet syndrome, nor the GAERS model of absence epilepsy." (PMID 37082241, 2023). "Of 9 individuals with SCN1A P, LP, or VUS variants, 3 had clinical Dravet syndrome; notably, 2 parents harbored these variants in mosaic form." (PMID 37471090, 2023). "A recent ASO with a similar mechanism has been developed and tested in a mouse model of Dravet syndrome and was shown to increase productive SCN1A mRNA transcripts sixfold and the voltage-gated sodium channel α subunit Nav.1.1 by over 50% in a dose dependent manner." (PMID 36365206, 2022). "Stoke Therapeutics is currently conducting a phase 1/2a study of STK-001, an 2MOE PS ASO designed to skip a nonproductive exon in SCN1A gene, in Dravet syndrome (Stoke, 2020)." (PMID 33996898, 2021). "The phenotype can resemble Dravet syndrome and according to some studies, PCDH19 variants are found in 25% of SCN1A-negative females exhibiting features of Dravet syndrome." (PMID 34842787, 2021). "Encouraging reductions in seizures and mortality were also seen in a mouse model of Dravet syndrome after ICV administration of ASO that increases expression of SCN1A transcripts by reducing non-productive splicing." (PMID 34690692, 2021). "PCDH19 mutations were initially thought to only affect females, however, in 2009, Depienne and colleagues described a SCN1A-negative male diagnosed with “Dravet syndrome”, as having a de novo deletion on chromosome Xq22.1 that spanned the entire PCDH19 gene." (PMID 29892053, 2019). "The phenotype, early infantile SCN1A encephalopathy, was not yet recognized, and Dravet-like features such as hemiclonic seizures led to the diagnosis of Dravet syndrome." (PMID 28794249, 2017). "Intriguingly, in a haploinsufficiency model of Dravet syndrome, directly upregulating Scn1a expression using long non-coding RNAs rescued the firing phenotype in PV cells and lowered seizure number and duration." (PMID 29069078, 2017). "Not all SCN1A epileptic encephalopathies are Dravet syndrome: Early profound < r226Met phenotype Mefiord HC, Schefier IE." (PMID 29291359, 2017). "Baseline characteristics of children with seizures following vaccinations, and with or without SCN1A-related Dravet syndrome." (PMID 23762420, 2013).
Dravet syndrome (continued). "Notably, our association is with a syndrome involving hippocampal damage, whereas typically no hippocampal damage is observed in patients with Dravet syndrome caused by deleterious changes affecting SCN1A, suggesting that SCN1A might influence epileptogenesis through various mechanisms." (PMID 24014518, 2013). "Characteristics of reported seizures following DTP-IPV(-)Hib vaccination in children with and without SCN1A-related Dravet syndrome." (PMID 23762420, 2013). "No prospective studies on the prevalence of SCN1A-related Dravet syndrome among children with vaccination-related seizures have been published yet." (PMID 23762420, 2013). "A novel PCDH19 p.D377N mutation was identified in one SCN1A-negative female patient with Dravet syndrome and a known PCDH19 p.N340S mutation in a female non-Dravet syndrome patient." (PMID 22848613, 2012). "Regarding Dravet Syndrome, screening for PCDH19 mutations should be performed for female patients when analysis of SCN1A (including a method searching for SCN1A micro-rearrangements) is negative." (PMID 21053371, 2011). "The high frequency of patients with PCDH19 found in this study justifies the molecular testing of this gene in SCN1A-negative patients, especially females, diagnosed as having Dravet syndrome." (PMID 19214208, 2009). "Considering that seizure triggers are common in Dravet syndrome, such as environmental heat (for example, infection, fever and immunization) and factors such as excitement and strong light, we suspected SCN1A haploinsufficiency, although bathing did not provoke seizures." (PMID 40903466, 2025). "In phase 1/2a trials of zorevunersen (STK-001), an antisense oligonucleotide that increases expression of NaV1.1 channels, median convulsive seizure frequency was reduced at 3 and 6 months after the last dose compared with baseline in children with SCN1A-positive Dravet syndrome." (PMID 41007820, 2025). "The SCN1A gene pathogenic variants are identified in the spectrum of disorders from the most severe non-Dravet DEEs (DEE6B, MIM 619317) Dravet syndrome (DRVT/DS, MIM 607208) to milder syndromes, such as generalized epilepsy with febrile seizures plus type 2 (GEFS+ 2/GEFSP2, MIM 604403)." (PMID 38339022, 2024). "However, SB2193 did not reduce spontaneous seizures in the Scn1a+/− mouse model of Dravet syndrome, nor absence seizures in the Genetic Absence Epilepsy Rat from Strasbourg (GAERS)." (PMID 37082241, 2023). "SCN1A; however, limited success in the treatment of Dravet syndrome persisted in part due to the lack of understanding that inhibitory interneurons and not pyramidal neurons had altered excitability as a result of LOF SCN1A mutations." (PMID 37292138, 2023). "First, we employed a heterozygous Scn1a+/− mouse model lacking one copy of the NaV1.1 protein that is used as a model for a variety of seizure types from simple febrile seizures to severe genetic disorders such as Dravet and Lennox–Gastaut syndromes." (PMID 31693171, 2020). "Since the PCDH19 and Dravet syndrome phenotypes show many similarities, testing a cohort of SCN1A-negative, male Dravet syndrome patients for mosaic PCDH19 pathogenic variants could give more insight in the true incidence." (PMID 28669061, 2017). "Our aim was to identify the gene(s) involved in SCN1A-negative patients with Dravet syndrome." (PMID 19214208, 2009). "Notably, VIP interneuron-specific SCN1A deletions replicated a number of Dravet syndrome symptoms but did not induce seizures, suggesting that VIP+ interneurons might be involved in managing behavior and network activity." (PMID 39916937, 2024). "Of particular interest, the significantly lowered PRS for intelligence in our cohort could imply that even with symptomatic treatment leading to seizure freedom, or with disease-modifying treatment increasing SCN1A expression, the full phenotype of Dravet syndrome may not be entirely reversible." (PMID 37006128, 2023).
Dravet syndrome (continued). "Notably, pharmacological inhibition of eEF2K in adult mice was also sufficient to normalize the EEG profile of Scn1a ± mice proposing eEF2K as a new pharmacological target not only for Dravet syndrome but also for several neuronal diseases in which eEF2K activity is altered." (PMID 34980259, 2022). "Seizures in children with SCN1A-related Dravet syndrome occurred more often with a body temperature below 38.5°C (57.9% vs. 32.6%, p = 0.020) and reoccurred more often after following vaccinations (26.7% vs. 4.0%, p = 0.003), than in children without a diagnosis of SCN1A-related Dravet Syndrome." (PMID 23762420, 2013).
Epileptic encephalopathy (86 papers, 2009 to 2026). A condition in which epileptiform abnormalities are believed to contribute to the progressive disturbance in cerebral function. "DS is a severe developmental and epileptic encephalopathy, typically caused by de novo mutations in the SCN1A gene, which encodes the alpha subunit of the voltage-gated sodium channel Nav1.1." (PMID 41158906, 2025). "In the present study, eight heterozygous SCN1A variants were identified in patients presenting with developmental and epileptic encephalopathies, predominantly DS and, in one case, WS." (PMID 41153369, 2025). "For example, families with pathogenic SCN1A variants can have heterogeneous phenotypes ranging from severe epileptic encephalopathy to mild febrile seizures, and various seizure types including both generalized and focal." (PMID 40047626, 2025). "SCN1A pathogenic variants account for approximately 70–80% of classical DS cases, underscoring their central role in this severe developmental and epileptic encephalopathy." (PMID 41153369, 2025). "Here, we report a family in which the biallelic inheritance of two novel SCN1A variants, N935Y and H1393Q, occurs in two siblings presenting with drug-responsive developmental and epileptic encephalopathy and born to heterozygous asymptomatic parents." (PMID 39200163, 2024). "Variants in the SCN1A gene can cause a spectrum of early-onset epileptic encephalopathies, in addition to FHM; therefore, our finding reasonably explains the proband phenotype, in which the main symptom was recurrent facial palsy." (PMID 37510386, 2023). "Our study suggests that cortical SD is a pathological manifestation in SCN1A-deficient epileptic encephalopathy." (PMID 37551713, 2023). "Febrile-associated epileptic encephalopathy is a large genetically heterogeneous group that is associated with pathogenic variants in SCN1A, PCDH19, SCN2A, SCN8A, and other genes." (PMID 35711923, 2022). "Patient 4 is a girl with a severe early/onset epileptic encephalopathy and compound heterozygous SCN1A missense variants (p.Thr1174Ser and p.Arg1928Gly)." (PMID 35328054, 2022). "Such a wide spectrum of epileptic disorders has ever been defined as in the case of SCN1A mutations where the electroclinical entity ranges from severe epileptic encephalopathy with generalized electrographic discharges to focal seizures with febrile illness." (PMID 34149607, 2021). "DS is a severe epileptic encephalopathy, most often resulting from de novo SCN1A mutations, and typically begins in infancy with seizures provoked by fever, including status epilepticus cognitive impairment, and poor response to available antiepileptic drugs." (PMID 32184723, 2020). "Mutations in SCN2A and more recently SCN3A are established monogenic causes of epileptic encephalopathy that, like SCN1A, cause dysfunction of the encoded ion-channels, which is believed to disturb the fine balance between neuronal excitation and inhibition." (PMID 30531953, 2018). "A case series of 9 children were identified with a profound developmental and epileptic encephalopathy and SCN1A mutation." (PMID 28794249, 2017). "Among cases, a SCN1A splice-donor de novo mutation was found among two probands, both ascertained for an epileptic encephalopathy." (PMID 26332131, 2015). "Mutations of the SCN1A gene, which encodes the voltage-dependent Na+ channel’s α subunit, are associated with diverse epileptic syndromes ranging in severity, even intra-family, from febrile seizures to epileptic encephalopathy." (PMID 38339022, 2024). "For example, the gain-of-function T226M mutation in Scn1a has been found in children with developmental and epileptic encephalopathy and gain-of-function mutations in Scn2a have been shown to elicit seizures, behavioral arrest, and behavioral abnormalities in mice." (PMID 35165201, 2022).
Epileptic encephalopathy (continued). "Indeed, a recent study of developmental and epileptic encephalopathies patients uncovered five pathogenic variants of the sodium voltage-gated channel alpha subunit 1 (SCN1A) gene, which encodes a type I voltage-gated sodium channel." (PMID 34899861, 2021). "Therefore, our findings regarding these genes are consistent with those of previous studies and confirm that patients with epileptic encephalopathy with SCN1A and SCN2A mutations respond well to KD, while patients with CDKL5 mutations respond poorly to KD." (PMID 30061856, 2018). "More rarely, SCN1A mutations are also found in other types of infantile epileptic encephalopathies." (PMID 26990884, 2016). "Following the seminal discovery of de novo SCN1A mutations as the cause in >80% of patients with Dravet syndrome, a paradigmatic epileptic encephalopathy, a number of other genes have been shown to account for other hitherto unexplained Epileptic Encephalopathies." (PMID 25014031, 2014). "SCN1A has a pleiotropic effect, since variants in this gene have been linked to several phenotypes, and heterozygous mutations in the SCN1A gene can cause a spectrum of early-onset epileptic encephalopathies (MIM #604403, #607208, #619317), FHM3 (MIM #609634), and autism spectrum disorders (ASD)." (PMID 37510386, 2023). "Taken together, our findings suggest that poison exon usage by Scn1a and Scn8a is a strategy to regulate channel expression during normal brain development, and that mutations recapitulating a fetal-like pattern of splicing cause reduced channel expression and epileptic encephalopathy." (PMID 33411788, 2021). "Subsequently, it was discovered that it is also associated with epileptic encephalopathy—DRVT —and that the vast majority of patients with SCN1A variants show this phenotype." (PMID 38785537, 2024). "Type and location of variants make a huge difference in the severity of SCN1A disorder, ranging from the mild phenotype (genetic epilepsy with febrile seizures plus, GEFS+) to the severe phenotype (developmental and epileptic encephalopathies, DEEs)." (PMID 38025388, 2023). "Allelic variants of sodium voltage-gated channel alpha subunit 1 (SCN1A) are closely associated with generalized epilepsy that includes febrile seizures and epileptic encephalopathy." (PMID 36142719, 2022). "This view is consistent with studies demonstrating that postnatal conditional Scn1a deletion can create an epileptic encephalopathy similar to the genomic model, and also that the disease phenotype can be reversed or ameliorated when Scn1a expression is recovered at a juvenile age." (PMID 37551713, 2023). "Gain of function mutations of SCN1A are associated with migraine, while loss of function mutations are associated with a broad range of epilepsy syndromes, ranging from the more mild GEFS+ to severe epileptic encephalopathies, including DS." (PMID 35523580, 2022). "Several pathogenic genes with de novo mutations, such as sodium voltage-gated channel alpha subunit 1 (SCN1A), are also involved in TLE, suggesting that de novo variants identified in epileptic encephalopathies might function in TLE." (PMID 34393975, 2021). "In addition, a novel and de novo SNV of c.2948delT (p.V983Afs*2) in SCN1A was detected in a boy with intractable complex partial seizures and epileptic encephalopathy, and history of status epilepticus." (PMID 28074849, 2017). "Interestingly, mutation of the corresponding leucine residue in SCN1A resulted in impaired channel inactivation, a common feature of SCN8A mutations in epileptic encephalopathy." (PMID 27900360, 2016).
Epileptic encephalopathy (continued). "In addition, the same types of mutation, and even the same mutations, are found in patients with DS and patients with other infantile epileptic encephalopathies (such as cryptogenic generalized or focal epilepsies), which has extended the clinical spectrum of SCN1A and the definition of DS." (PMID 19214208, 2009). "Both deletions and duplications, involving each of SCN1A, SCN2A, and SCN3A, have been presented previously in cases with severe epileptic encephalopathies and developmental delay." (PMID 31694722, 2019). "Although mutations of SCN1A have also been described in patients with epileptic encephalopathy, intellectual disability, and ASD8,9,18,21,22, the distributions of Nav1.1 and Nav1.2 are highly distinct from each other in brain." (PMID 30175250, 2018). "Genetic testing of PCDH19 may be useful for all patients with Dravet-like epileptic encephalopathy who have a negative test for SCN1A." (PMID 38891919, 2024). "In the present study, we did not include cases with SCN1A-related epileptic encephalopathies in the OXC group, so that the iatrogenic exacerbation of seizures and the subsequent outcome bias could be avoided." (PMID 35720076, 2022).